TRAV23DV6 (T cell receptor alpha variable 23/delta variable 6)
Description:
V region of the variable domain of T cell receptor (TR) alpha chain that participates in the antigen recognition. Alpha-beta T cell receptors are antigen specific receptors which are essential to the immune response and are present on the cell surface of T lymphocytes. Recognize peptide-major histocompatibility (MH) (pMH) complexes that are displayed by antigen presenting cells (APC), a prerequisite for efficient T cell adaptive immunity against pathogens. Binding of alpha-beta TR to pMH complex initiates TR-CD3 clustering on the cell surface and intracellular activation of LCK that phosphorylates the ITAM motifs of CD3G, CD3D, CD3E and CD247 enabling the recruitment of ZAP70. In turn ZAP70 phosphorylates LAT, which recruits numerous signaling molecules to form the LAT signalosome. The LAT signalosome propagates signal branching to three major signaling pathways, the calcium, the mitogen-activated protein kinase (MAPK) kinase and the nuclear factor NF-kappa-B (NF-kB) pathways, leading to the mobilization of transcription factors that are critical for gene expression and essential for T cell growth and differentiation. The T cell repertoire is generated in the thymus, by V-(D)-J rearrangement. This repertoire is then shaped by intrathymic selection events to generate a peripheral T cell pool of self-MH restricted, non-autoaggressive T cells. Post-thymic interaction of alpha-beta TR with the pMH complexes shapes TR structural and functional avidity.
Synonyms: TRAV23/DV6; TCRAV17S1; hADV23S1
Gene: T-cell receptor variable (V) gene on chromosome 14 (22,086,407 to 22,086,961, forward strand). Ensembl gene ENSG00000211803.
Subcellular location: Cell membrane
Gene Ontology:
Molecular function: peptide antigen binding
Cellular component: plasma membrane
Homologues: Orthologues: mouse Trav14-3 (73% identical), mouse Trav14-2 (71% identical), mouse Trav14d-3-dv8 (71% identical), mouse Trav14n-3 (71% identical), mouse Trav14d-2 (69% identical), mouse Trav14n-2 (69% identical), mouse Trav14d-1 (68% identical), mouse Trav14n-1 (68% identical), mouse Trav14-1 (67% identical). Paralogues in human: TRAV29DV5 (58% identical), TRAV12-3 (45% identical), TRAV12-2 (39% identical), TRAV12-1 (34% identical).